BCL2 (BCL2 apoptosis regulator)
Diseases named in the same sentence as BCL2 in open-access papers (continued):
Sharing a sentence is not in itself a finding about the gene and the disease.
tumor (continued). "At the time of sacrifice (Day 23 after tumor inoculation), mRNA expression of the genes coding for p16 and Bcl2 was lower in ABT‐263‐treated, old mice than in controls." (PMID 37997569, 2023). "We also examined the expression of target genes of NF-kB pathway, including BCL2, MYC, and CCND1, which are also associated with tumor proliferation." (PMID 37716704, 2023). "Inflammatory mediators such as interleukin (IL)-6 can also mediate tumor proliferation by activating the antiapoptotic protein Bcl-2." (PMID 37373544, 2023). "It has been reported that the combined use of Bcl2 siRNA and low doses of doxorubicin enhanced autophagy‐mediated cell death and tumor inhibition in MCF‐7 cell line." (PMID 36760166, 2023). "Compared with the Mod group, the expression levels of MMP-9, MMP-2, VEGF, bFGF, Bax, and Bcl-2 in tumor tissues were reversed by 67%, 74%, 50%, 63%, 80%, and 51%, respectively, after GFG combined with CTX treatment (p < 0.05)." (PMID 37049720, 2023). "To investigate the effect of FYLM on tumor growth, we detected the levels of cell proliferation, cell cycle, and apoptosis-related protein Ki-67, cyclin B1, Bcl-2 and cleaved Caspase-3 in xenograft mouse tumor tissues by western blot and immunohistochemistry." (PMID 36744262, 2023). "The combined administration of BCL-2 inhibitors with chemotherapeutic drugs in solid tumors is capable of overcoming chemoresistance and preventing tumor growth." (PMID 37894324, 2023). "Enhanced G6PD activity has been linked to the upregulation of anti-apoptotic factors such as Bcl-2 and Bcl-xL, which contribute to promoting cell growth and tumor development." (PMID 37627157, 2023). "Altogether, these results suggest that BCL2 inhibition activates cDC1s both in tumor-bearing mice and in human." (PMID 37623817, 2023). "Both B-cell receptor signaling and BCL2 have been reported to promote tumor survival and drug resistance in DLBCL35,36." (PMID 37308475, 2023). "This anti-apoptogenic activity makes the BCL-2 protein behave as an oncogene and a potent tumour promoter." (PMID 37686461, 2023). "Known transcripts exported and translated with the help of eIF4E include VEGF, which facilitates angiogenesis to increase tumour blood supply, BCL-2, which plays a role in cell survival, and growth stimulators c-Myc and Cyclin D1." (PMID 36671496, 2023). "PIM1 can enhance the activity of Bcl-2 by phosphorylating B cell lymphoma-2 protein (Bcl-2), thus promoting the proliferation of tumor cells and further promoting the invasion and migration of tumors." (PMID 36871027, 2023). "The expressions of MMP-9, VEGF, Bcl-2, and Cyclin D1, involved in tumor progression, were found to increase in the radiation-alone group, but they decreased in the Rh2-alone and combination groups." (PMID 37764996, 2023). "BCL-2 inhibitors have evolved into an important means of treating cancers by inducing tumor cell apoptosis." (PMID 37894324, 2023). "For example, BCL2 is abnormally expressed in CRC and linked to tumor growth and development, while BAX is a BCL2 family protein and regulates cell development and apoptosis." (PMID 37151391, 2023). "Suppressing HMGB1 expression down-regulated the molecular level and activity of Bcl-2, blocked the binding of Bcl-2 to autophagy gene Beclin1, and inhibited autophagy, thus promoted the apoptosis of tumor cells." (PMID 37518006, 2023). "Venetoclax enhanced the suppressive effect of gemcitabine on tumor growth through downregulation of BCL-2 overexpression induced by gemcitabine." (PMID 37894324, 2023). "Meanwhile, an in vivo study found that MIC-1 suppressed the growth of xenograft tumours and enhanced the Bax/Bcl-2 ratio in tumour tissues in mice." (PMID 37570837, 2023).
tumor (continued). "The tumor cells were positive for c-Myc (Y69) and Bcl2, and the Ki-67 proliferation index was up to 80%." (PMID 37884941, 2023). "The expression of Bcl-2, which inhibit cellular apoptosis, was downregulated in tumor tissues from MCR group when compared with CTR group, whereas the expression level of cleaved PARP, a marker for apoptosis, was higher in MCR group than in CTR group." (PMID 37268653, 2023). "Bcl-2, which plays an important function in the process of resisting tumor apoptosis, is an anti-apoptotic protein with key functions." (PMID 37524857, 2023). "Inhibition of apoptosis using either BCL2 or BCL‐xL promoted expansion of tumor cell populations in vitro but, surprisingly, constrained their growth in vivo." (PMID 37553811, 2023). "It was also found that AGE causes a decrease in the chemo-resistance of cancer cells by down-regulation of Bcl-2 and up-regulation of E-cadherin, which leads to a decrease in tumor invasiveness." (PMID 36661532, 2023). "Resveratrol has also been shown to inhibit tumor growth by down-regulating Bcl-2 as well as by decreasing DNA synthesis in HL60 cell line." (PMID 36672729, 2023). "Despite differences in study cohorts, previous studies have reported the prognostic value of biomarkers such as BCL2, tumor-infiltrating lymphocytes, specific microRNAs, and circulating tumor cells." (PMID 37760420, 2023). "Compared with the CTX group, the expression levels of MMP-9, MMP-2, VEGF, bFGF, Bax, and Bcl-2 in tumor tissues were reversed by 47%, 72%, 49%, 60%, 57%, and 48%, respectively, after high-dose GFG combined with CTX treatment." (PMID 37049720, 2023). "Intrinsic or mitochondrial apoptotic pathway is dependent on proteins from the Bcl-2 family, where protein Bcl-2 is a key inhibitor of apoptosis and is usually found over-expressed in tumours, such as CRC." (PMID 37108599, 2023). "In this context, it will be important to monitor the immunostimulatory effects of BCL2 inhibitors on circulating and tumor-infiltrating cDC1 cells." (PMID 37623817, 2023). "The number of tumor cell value-added, tumor cell apoptosis rate, thymus index (TI), and Bcl-2 gene expression level were the main indicators to be analyzed." (PMID 37180714, 2023). "Due to the important roles of antiapoptotic Bcl-2 proteins for tumor cell survival, combinations of inhibitors for antiapoptotic Bcl-2 proteins (BH3 mimetics) with MAPK inhibitors appear to be promising strategies." (PMID 36902392, 2023). "An additional scoring (aggression score) system based on the expression of the ANLN and BCL2 genes correlated the ERness score with the tumor grade to predict the intrinsic aggressiveness of the tumors." (PMID 36834918, 2023). "NFs also inhibit HNSCC tumor growth and de-repress BCL2 expression in vivo through the transfer of exosomes containing miR-3188, but this miRNA is also significantly reduced in CAFs." (PMID 37046676, 2023). "The development of BCL-2 inhibitors as a pivotal approach in cancer treatment lies in their ability to effectively trigger apoptosis in tumor cells." (PMID 37894324, 2023). "Increased COX activity, oxygen consumption and mitochondrial respiration were found in tumor cells overexpressing Bcl-2." (PMID 37954849, 2023). "The protein expression of pro and anti-apoptotic markers including Bax, Bcl-2, and caspase-3 was analyzed by western blotting on tumor tissue in CT26-Bearing Mice." (PMID 38202610, 2023). "Venetoclax (VTC) is a selective BCL-2 inhibitor that directly targets the BCL-2 protein, modulating the mitochondrial apoptotic pathway and inducing tumor cell death." (PMID 38026941, 2023). "In a mouse xenograft tumor model, the authors observed significant downregulation of the BCL2 gene that coincided with outstanding anti-tumor effects in treated mice." (PMID 37111795, 2023). "Studies in vitro showed that when tumor cells were pre-sensitized by a Bcl-2 inhibitor called venetoclax, CD19 CAR-T cells’ killing efficiency was significantly increased." (PMID 36701037, 2023).
tumor (continued). "Impairing mitochondrial apoptosis via knockout of Bak and Bax, forced Bcl-2 and Bcl-XL expression, or caspase inhibition protected several tumor models from CAR T killing." (PMID 37055388, 2023). "BCL-2 expression in immunochemistry on tumor samples at relapse and the BCL2 gene status was evaluated in all patients." (PMID 37935707, 2023). "By contrast, the combined treatment of cisplatin and baicalein exerted anti-tumor effects through inhibition of the phosphorylation of Akt, mTOR and Erk, and the expression of Bcl-2." (PMID 37940982, 2023). "When STAT3 is inhibited in tumor cells, the expression of Bcl-2, which is an anti-apoptotic gene, is reduced, and the apoptotic caspase 3 pathway is activated." (PMID 37369757, 2023). "Venetoclax (Ven), an oral Bcl-2 inhibitor, selectively binds to Bcl-2 to release proapoptotic proteins in tumor cells." (PMID 37173750, 2023). "Experiments in vitro verified that rhIL-37 reduced IL-6, pSTAT3Y705, cyclin D1, and HIF-1α levels that contributed to tumor cells proliferation and migration, and Bcl-2 level that inhibited apoptosis in A498 and Caki-1 cells." (PMID 37928545, 2023). "The assumption is that during tumor progression, Bcl-2 expression decreases due to its inhibitory effect on the progression of the cell cycle, thus leading to a reduction in the inhibition of apoptosis." (PMID 36766867, 2023). "Gene expression profiling of MM cells treated with ARd results in upregulation of IRF1, which is a tumor suppressor that inhibits BCL2 transcription, but increases expression of caspases and enhancement of mitochondrial-mediated tumor cell apoptosis." (PMID 36672426, 2023). "CXCL12 up‐regulate the anti‐apoptotic proteins Bcl‐2 and Survivin in tumor cells, resulting in drug resistance." (PMID 37578396, 2023). "Consistent with the induction of apoptosis, we found a significant decrease in phospho-BAD and Bcl-2 in the tumor tissues of p402 mAb- and p40 mAb-treated PDX mice as compared to those of untreated PDX mice." (PMID 38136341, 2023). "Upon binding to Bcl-2, they inhibit its activity, which restores apoptotic processes in tumor cells." (PMID 37374055, 2023). "To further elucidate the elraglusib-mediated effects on tumor cell survival we probed for survival factors Bcl-2 and Survivin and noted decreases in protein expression in both cell lines, especially at the later timepoints (48, 72 h)." (PMID 37446056, 2023). "Many other authors reported that apoptosis is induced by HPF in different tumor types, with mechanisms involving other pro- or antiapoptotic effector proteins, or by mediating the Bcl2/Bcl-xL axis." (PMID 36674794, 2023). "Preclinically, this broad-spectrum HDACi decreased the expression of both MYC and BCL2 and was able to elicit a significant reduction in tumor growth." (PMID 37457123, 2023). "As the most extensively investigated BCL-2 inhibitor, venetoclax is highly selective for BCL-2 and can effectively inhibit tumor survival." (PMID 37894324, 2023). "At the same time, more cells remained in the G2/M phase, and the proportion of cells in the S phase decreased, which has been proven to be closely related to the expression of BCL-2 in tumor tissue and improving the level of serum alkaline phosphatase." (PMID 37383719, 2023).
tumor (continued). "Upregulation of the Bcl-2 antiapoptotic proteins is a frequent method by which cancer cells can resist apoptosis since the Bcl-2 gene has a crucial role in controlling apoptosis in the initiation, progression, and resistance to targeted therapy of tumor." (PMID 37516866, 2023). "Cytoplasmic immunoreactivity in the “Bcl-2 positive” subset of cancers ranged from 1 to 100% of the overall tumour tissue (mean value 70%)." (PMID 38004573, 2023). "By decreasing the BCL2/Bax ratio and activating caspases, vitexin inhibits tumour growth and spread by killing cancer cells." (PMID 36937314, 2023). "Then, the release of FEGCG and MPI can not only regulate PD-L1 signaling with IRF, STAT-1/pSTAT-1, and PD-L1 expression, but also induce apoptosis signaling with Bcl-2 and Bax expression in tumor cells." (PMID 37277118, 2023). "The majority of human prostate tumors overexpress Bcl-2, and we already know from the literature that overexpression is responsible for tumor resistance to radiotherapy and chemotherapy as a predominant antiapoptotic protein." (PMID 37241040, 2023). "Since PPARα activation can induce apoptosis in a variety of tumor cells and venetoclax inhibits the anti-apoptotic protein Bcl-2, the apoptosis of KG-1α cells was assessed by flow cytometry using Annexin V/PI staining." (PMID 37644011, 2023). "And combination of KLK2 and ARA70 can also inhibit tumor cell apoptosis and promote tumor progression by bax/bcl2/caspase-3 signaling pathway." (PMID 37593117, 2023). "Venetoclax, a Bcl-2 inhibitor, has shown robust anti-tumor effects against several malignancies, and is already FDA approved." (PMID 37163552, 2023). "When compared to tumor-free rats, the treatment with S. cerevisiae conjugated to gold nanospheres (GNSs) lowered Bcl-2 levels while increasing FasL, Bax, cytochrome c, and caspases 8, 9, and 3 levels." (PMID 36877301, 2023). "Taken together, WCP exerted its anti-tumor effects probably through the Cyto-c/Caspase8/3 and IL-10/STAT3/Bcl2 pathway in H22-tumor-bearing mice." (PMID 37110586, 2023). "SAMC induces the family of Bcl-2 genes to activate the apoptosis of tumor cells through the modulation of the MAPK pathway and the release of the mitochondrial cytochrome c." (PMID 36661532, 2023). "The results showed that treatment with aconitine led to a significant reduction in tumor cell proliferation, a noteworthy increase in the rate of apoptosis among tumor cells, a decrease in the thymus index, and a reduction in the expression level of Bcl-2." (PMID 37180714, 2023). "According to some studies, IL-6 can have indirect anti-tumor activity through Bcl-2 and immunoglobulin production, but also can stimulate cytokine secretion within the tumor and limit the effectiveness of immunotherapy." (PMID 37514190, 2023).
tumor (continued). "on the other hand, it inhibits Bcl-2 expression and activates the downstream Caspase-3 to promote tumor cell apoptosis by regulating the NF-κB signaling pathway." (PMID 37180714, 2023). "A cationic amphiphile containing an endosomal pH-sensitive imidazole ring can be used to deliver both paclitaxel and a Bcl-2 siRNA, significantly inhibiting cellular proliferation and reducing tumor growth." (PMID 37416764, 2023). "Western blotting analysis confirmed that NTN4 overexpression downregulated β-catenin, Vimentin, and Bcl-2 expression in the tumor tissues." (PMID 37345154, 2023). "BAX is an apoptosis-promoting gene in the BCL-2 gene family, and its overexpression can antagonize the protective effects of BCL-2 and induce the apoptosis of tumor cells." (PMID 37280630, 2023). "The expression levels of BCL-2 (P < 0.01), clCasp3 (P = 0.04), Ki-67 (P = 0.04) and CD81 which has been associated with chemoresistant MM tumor cells (P < 0.01), were significantly higher in RRMM than in NDMM samples consistent with a more aggressive disease." (PMID 37217482, 2023). "Hypoxia in a tumor cell is related to apoptosis as hypoxia-inducible factor-alpha (HIF-α) regulates the apoptotic genes (BCL-2, BAX, caspase 3, caspase 8) as well as a survival signaling pathway, i.e., NF-kB." (PMID 36715825, 2023). "In turn, NRF2 promotes tumor cell survival through its antioxidant effect and transcriptional upregulation of Bcl-2 and Bcl-xL." (PMID 37906282, 2023). "Using Se-PC as a photosensitizer in tumors, pyroptosis was the primary type of tumor death by increasing the activity of Caspase-1 and Caspase-3 and reducing the activity of Caspase-8 and Bcl-2." (PMID 37994159, 2023). "BET proteins also play important roles in tumor development by regulating the expression of multiple transcription factors, and two of them are c-Myc and Bcl-2." (PMID 37686632, 2023). "DLBCL/HGBL-MYC/BCL2 are aggressive neoplasms diagnosed in advanced disease stages in the majority of patients." (PMID 37190213, 2023). "The results showed that HOTAIR targets the JAK/STAT signaling pathway, a mitochondria-dependent signaling pathway involving Bcl-2 and Bax, to interfere with tumor growth and apoptosis." (PMID 36924407, 2023). "Then, TGFβ1 binds to TGFBR1/R2 in tumor cells to activate Smad2/3 signalling to increase the expression of PAI-1, which further activates PI3K/AKTThr308, p-Bad and Bcl-2 to support tumor cell survival in circulation." (PMID 37705745, 2023). "In our study, miR-34c-5p was shown to indeed regulate BCL-2 to play a tumor suppressor role in LUAD." (PMID 37670265, 2023). "The overexpression of miR-15a was found to repress the tumor cells’ invasion and migration via regulation of Bcl-2 and mitochondrial membrane potential." (PMID 37720343, 2023). "Higher levels of COX activity, oxygen consumption and mitochondrial respiration were demonstrated in tumor cells overexpressing Bcl-2." (PMID 37954849, 2023). "Western blot results showed that both SS and Ent downregulated Bcl-2 protein expression levels and upregulated Caspase-3 and Cyt C protein expression levels in tumor cells, and SS and Ent had a synergistic effect in inducing apoptosis." (PMID 37764423, 2023). "Results showed a decrease in BCL2 levels in all treated groups compared to the control indicating apoptosis of tumour cells in the treated groups." (PMID 38022682, 2023). "In conclusion, genetic and pharmacological BCL2 inhibition unveils a DC-specific immune checkpoint that restrains tumor immunosurveillance." (PMID 37623817, 2023).